KDM5D (lysine demethylase 5D)
Description:
Histone demethylase that specifically demethylates 'Lys-4' of histone H3, thereby playing a central role in histone code. Does not demethylate histone H3 'Lys-9', H3 'Lys-27', H3 'Lys-36', H3 'Lys-79' or H4 'Lys-20'. Demethylates trimethylated and dimethylated but not monomethylated H3 'Lys-4'. May play a role in spermatogenesis. Involved in transcriptional repression of diverse metastasis-associated genes; in this function seems to cooperate with ZMYND8. Suppresses prostate cancer cell invasion. Regulates androgen receptor (AR) transcriptional activity by demethylating H3K4me3 active transcription marks.
Synonyms: HY; HYA; JARID1D; KIAA0234; SMCY
Tractability: Small molecule: a high-quality ligand is known. PROTAC: UniProt records ubiquitination sites on it; ubiquitination databases record sites on it; a small molecule that binds it is known.
Target class: Enzyme; Oxidoreductase
Gene: Protein-coding gene on chromosome Y (19,703,865 to 19,744,989, reverse strand). Ensembl gene ENSG00000012817.
Subcellular location: Nucleus
Subcellular location (Human Protein Atlas): Nucleoli fibrillar center
Pathways (Reactome):
Chromatin organization: HDMs demethylate histones
Gene Ontology:
Molecular function: histone H3K4 demethylase activity; nuclear androgen receptor binding; protein binding; histone demethylase activity; histone H3K4me/H3K4me2/H3K4me3 demethylase activity; DNA binding
Biological process: regulation of androgen receptor signaling pathway; regulation of DNA-templated transcription; chromatin remodeling
Cellular component: nucleus; chromatin; nucleoplasm
Homologues: Orthologues: chimpanzee KDM5D (99% identical), macaque KDM5D (96% identical), dog KDM5C (86% identical), mouse Kdm5d (81% identical), rat Kdm5d (80% identical), pig KDM5D (80% identical), guinea pig KDM5C (68% identical), Drosophila melanogaster Kdm5 (41% identical), Caenorhabditis elegans rbr-2 (27% identical), zebrafish kdm4c (13% identical). Paralogues in human: KDM5C (86% identical), KDM5A (52% identical), KDM5B (45% identical), JARID2 (14% identical), KDM4A (13% identical), KDM4B (13% identical), KDM4C (12% identical), KDM4D (9% identical), KDM4F (8% identical), KDM4E (8% identical).
Diseases named in the same sentence as KDM5D in open-access papers:
KDM5D is named in the same sentence as 65 diseases in open-access papers, as found by Europe PMC text mining. Sharing a sentence is not in itself a finding about the gene and the disease. The quoted sentences say what the papers report.
prostate carcinoma (20 papers, 2011 to 2025). A carcinoma that arises from epithelial cells of the prostate gland. "KDM5D, also known as JARID1D, is a histone demethylase associated with the suppression of the invasive capacity of prostate cancer cells." (PMID 38673816, 2024). "Loss of the histone demethylase KDM5D (lysine‐specific demethylase 5D) leads to in vitro resistance of prostate cancer cells to androgen deprivation therapy (ADT) with and without docetaxel." (PMID 36087093, 2022). "One potential cause of low KDM5D expression in advanced prostate cancer is complete copy number loss given its localization on the Y chromosome." (PMID 36087093, 2022). "Importantly, the total or partial loss of the Y chromosome, including the KDM5D locus, has been observed not only in prostate cancer but also in ccRCC and lung cancer in males, and lower KDM5D expression is associated with poor prognosis." (PMID 35805040, 2022). "According to a previous study, KDM5D plays a critical role in prostate cancer by regulating the response to androgen deprivation therapy (ADT) and taxane treatments." (PMID 39239542, 2024). "KDM5D has been shown to prevent tumorigenesis, progression, and drug response in prostate cancer and gastric cancer." (PMID 35132955, 2022). "In prostate cancer, KDM5D suppresses the invasive phenotype by reducing the expression of metastasis-associated genes, such as MMPs and Slug, by interacting with ZMYND8 and removing H3K4me3 marks." (PMID 35805040, 2022). "The ZMYND8-induced suppression of invasiveness and metastasis in prostate cancer cells was demonstrated to be through cooperating with its transcriptional corepressor KDM5D." (PMID 33670804, 2021). "KDM5D/JARID1D is the least well investigated demethylases from the KDM5 subfamily, but has been implicated in prostate cancer progression." (PMID 34220955, 2021). "ZMYND8 and KDM5D act as general negative regulators of enhancers in prostate cancer cells, and they antagonize the expression of these genes by recognizing the gene-activation-related dual-histone marker H3K4me1-H3K14ac." (PMID 33670804, 2021). "In conclusion, our results, for the first time, showed the isoform/transcript-specific expression of KDM5D in the prostate cancer cell lines." (PMID 26728332, 2016). "In this light, the aim of this study was to investigate isoform/transcript-specific expression profiles of KDM5D in three prostate cancer cell lines, Du-145, LNCaP, and PC3." (PMID 26728332, 2016). "The principal aim of this study was to investigate the KDM5D isoform-specific expression pattern in three human prostate cancer cell lines (DU-145, PC3, and LNCaP) with different behaviors in tumourgenicity and other properties." (PMID 26728332, 2016). "The present study, for the first time, not only showed the expression profiles of KDM5D isoforms in prostate cancer cell lines but also evaluated the effects of the gene regulatory network on the expression profile of this gene." (PMID 26728332, 2016). "A deletion analysis of Y chromosome-specific genes in human prostate cancer revealed that the KDM5D gene is deleted in 52% of cases, demonstrating its involvement in cancer pathogenesis." (PMID 26728332, 2016). "This pattern suggests that the decrease in KDM5D could contribute to the development and progression of prostate cancer, facilitating invasion and metastasis." (PMID 38673816, 2024). "Indeed, KDM5D expression predicts the response to docetaxel in patients with metastatic castration-resistant prostate cancer." (PMID 35805040, 2022). "Together, this suggests an interaction between AR activity and KDM5D in prostate cancer biology." (PMID 36087093, 2022). "KDM5D had been suggested to be a tumor suppressor in prostate cancer, but its role in hematopoietic malignancies was unknown." (PMID 35132955, 2022). "In addition, many genes, including KDM5D, have been shown to modulate docetaxel sensitivity in prostate cancer." (PMID 34148031, 2021).
prostate carcinoma (continued). "KDM5D has also been reported to have a tumour suppressor function in prostate cancer." (PMID 29454353, 2018). "A recent study provides evidence that KDM5D plays an important role in determining docetaxel sensitivity, which is used in treating prostate cancer, by interacting with androgen receptor signalling and that its expression level is associated with clinical outcomes." (PMID 29454353, 2018). "Thus, the ATR inhibitor is sensitive to KDM5D-defective prostate cancer." (PMID 35805040, 2022). "Assessments of the baseline protein expression levels of KDM5D and MYBL2 in a panel of prostate cancer cell lines revealed the two cell lines with detectable KDM5D, LNCaP, and CWR22Rv1, had the lowest MYBL2 expression." (PMID 36087093, 2022). "In DU145 prostate cancer cells, in addition to KDM5C, ZMYND8 interacts with KDM5D, to act as transcriptional co-repressors, involved in regulating metastasis-linked genes." (PMID 33670804, 2021). "In the present study, the specific primers for quantitative RT-PCR were developed to detect KDM5D isoforms-I and -III, and to investigate their expression pattern in the prostate cancer cell lines." (PMID 26728332, 2016). "This notion was in line with a previous study that demonstrated KDM5D was involved in the regulation of ATR-dependent DNA damage repair of prostate cancer as shown by increasing CHK1 and cell division cycle 25C phosphatase (CDC25c) protein expression in response to KDM5D knockdown." (PMID 36982384, 2023).
gastric cancer (9 papers, 2022 to 2025). A primary or metastatic malignant neoplasm involving the stomach. "In contrast, KDM5D inhibits the invasion and metastasis of prostate cancer, and its overexpression can reduce the invasive ability of gastric cancer." (PMID 35493099, 2022). "The mechanism of action of KDM5D as a tumor suppressor gene has been investigated in gastric cancer (GC)." (PMID 34983649, 2022). "KDM5D regulates the epithelial-mesenchymal transformation and metastasis of gastric cancer, which is a novel target for cancer treatment." (PMID 36034939, 2022). "After first determining that patients with gastric cancer have significantly lowered KDM5D protein levels and that this trait is strongly correlated with more severe clinical characteristics in these patients Shen and colleagues sought to elucidate the mechanistic connection between these two items." (PMID 41214505, 2025). "Notably, the downregulation of KDM5D induces an aggressive phenotype in prostate and gastric carcinomas." (PMID 37974379, 2024). "Importantly in gastric cancer, KDM5D was found to inhibit the EMT program." (PMID 41214505, 2025).
colorectal cancer (8 papers, 2022 to 2026). A primary or metastatic malignant neoplasm that affects the colon or rectum. "Insights into key drivers of sex-specific cancers has recently been reported for colorectal cancers in which upregulation of Y-chromosome encoded histone demethylase KDM5D was shown to be largely responsible for the sex-specific differences in cancer rates and mortality." (PMID 38779538, 2024). "KDM5D downregulation has been linked to a poor survival rate in colorectal cancer." (PMID 37218871, 2023). "Protein encoded by KDM5D seems to act on E2F1 through demethylation, thereby suppressing cell growth and metastasis in some form of colorectal cancer." (PMID 38279299, 2024). "KDM5D overexpression effectively suppressed colorectal cancer development and metastasis in vitro and in vivo." (PMID 37218871, 2023). "KDM5D has also been shown to inhibit the invasion and metastasis of gastric and colorectal cancer cells, as well as to prevent DNA damage in hematopoietic stem and progenitor cells and leukemogenesis." (PMID 35805040, 2022). "Recently, Kdm5d was found to be a key driver of colorectal carcinoma (CRC) outcome and metastasis." (PMID 41580387, 2026). "Decreased KDM5D expression has also been observed in gastric and colorectal cancers." (PMID 35805040, 2022). "In addition, the Y chromosome gene KDM5D drives male-specific metastasis and worse outcomes in colorectal cancer harboring KRAS alterations, which activates STAT4 to increase KDM5D, repressing the expression of genes governing cell adhesion and immune recognition." (PMID 39751827, 2025). "Additionally, KDM5D inhibited tumor growth in colorectal cancer by demethylating E2F1 and suppressing FKBP4 transcription, thereby suggesting that it could possibly serve in the management of colorectal cancer in males." (PMID 37218871, 2023).
lung carcinoma (6 papers, 2021 to 2025). "Our findings identify tumour deficiency of KDM5D as a prognostic marker and credible mechanism underlying sex disparity in lung cancer." (PMID 34127738, 2021). "We sought to isolate the relationship between KDM5D deficiency and prognosis in lung cancer by fitting a multivariate Cox proportional hazards model in the discovery dataset." (PMID 34127738, 2021). "It was found that KDM5D inhibits the activation of p38ɑ by directly demethylating it and ultimately inhibits lung cancer progression both in vitro and in vivo." (PMID 41214505, 2025). "Notably, a recent report identified KDM5D as a demethylase of p38α at K165, and demethylation at K165 inhibited p38α and suppressed lung cancer progression." (PMID 41308413, 2025). "Moreover, genes KDM5D, UTY, and NF1 have demonstrated gender differences in lung cancer, while PPP6C and IGF1R exhibit sex-biased expression in melanoma, and the NRAS gene may play sex-specific roles in acute myelogenous leukemia." (PMID 39541191, 2024).
bladder cancer (5 papers, 2010 to 2025). "The authors also found that the faster tumor growth associated with LOY was associated with KDM5D loss and that Y-low bladder cancers had higher infiltration of exhausted and progenitor exhausted T cells." (PMID 38398136, 2024). "In clinical practice, detecting the loss of KDM5D and UTY could serve as valuable prognostic indicators, aiding in assessing the clinical aggressiveness of bladder cancer and guiding treatment decisions." (PMID 39594721, 2024). "This underscores the potential significance of assessing the expression of ChrY genes, particularly UTY and KDM5D, as a means of identifying bladder cancer patients who may benefit from ICI therapy in order to achieve improved response rates and enhanced survival outcomes." (PMID 39594721, 2024). "In bladder cancer, LOY is shown to result in inactivation of tumor suppressors such as KDM5D, leading to cancer immune evasion and T-cell exhaustion." (PMID 39194178, 2024).
breast carcinoma (5 papers, 2016 to 2025). "We first analyzed CNAs and mutations in 98 PHF genes (excluding KDM5D on chromosome Yq11) compiled from 960 breast cancer specimens in The Cancer Genome Atlas (TCGA) via cBioPortal." (PMID 28055972, 2017). "KDM5D is located in the Y chromosome and thus not expressed in breast cancer cells derived from female patients." (PMID 30080846, 2018). "KDM5D was not examined because KDM5D is located on the Y chromosome and therefore is not expressed in the breast cancer cell lines derived from female patients." (PMID 27224921, 2016). "We also analyzed the correlation between copy number and mRNA level of 97 PHFs (excluding those of KDM5D and KMT2B, as their RNA-sequencing data were not available) from TCGA breast cancer specimens." (PMID 28055972, 2017).
prostate tumors (4 papers, 2020 to 2025). "They showed that serine/threonine protein kinase ATR inhibitors could be a new therapeutic approach in aggressive prostate tumors deficient in KDM5D." (PMID 34983649, 2022). "Furthermore, KDM5D levels were highly reduced in metastatic prostate tumors compared with normal tissues and primary prostate tumors." (PMID 34983649, 2022).
Azoospermia (3 papers, 2016 to 2022). Absence of any measurable level of sperm,whereby spermatozoa cannot be observed even after centrifugation of the semen pellet. "KDM5D is one of the AZFb region genes on Y-chromosome, similar to USP9Y, it has been linked to azoospermia and spermatogenic failure." (PMID 34190021, 2022). "Finally, the DDX3Y gene, along with KDM5D and EIF1AY, are azoospermia factors (AZFa)." (PMID 31817322, 2019).
colon cancer (3 papers, 2014 to 2024). "Recently, KDM5D has been identified as a new Y-linked gene involved in sex differences in colon cancer and bladder cancer." (PMID 38095719, 2024). "An overexpression of KDM5D, a histone demethylase, by the transcription factor STAT3 results in epigenetic regulatory changes, leading to increased colon cancer metastasis in a mouse model." (PMID 38095719, 2024).
lymph node metastasis (3 papers, 2022 to 2024). "SCCs with KDM5D copy number loss were significantly associated with lymph node metastasis (p = 0.0107) and late pathological stage (p = 0.0085)." (PMID 37974379, 2024). "However, the expression levels of KDM5D were exclusively associated with the gender of PDAC patients, and not with other clinical factors such as tumor stage, grade, and lymph node metastasis." (PMID 37880235, 2023).
acute myeloid leukemia (2 papers, 2024 to 2025). Acute myeloid leukemia (AML) is a group of neoplasms arising from precursor cells committed to the myeloid cell-line differentiation. "Interestingly, KDM5A/B/C were all reported to induce acute myeloid leukemia (LAML), while KDM5D has not been reported in literature to relate to LAML yet." (PMID 41431699, 2025).
coronary artery disease (2 papers, 2019 to 2020). "In addition, although more extensive analysis is necessary, lnc-KDM5D-4 has been suggested to be associated with the accumulation of cholesterol resulting in atherosclerosis and coronary artery disease (CAD)." (PMID 33172104, 2020). "And a lncRNA at the KDM5D intergenic position (Y:20,519,948–20,524,433) was found in a screen using the human male cell line HepG2 to model coronary artery disease." (PMID 31608120, 2019).
head and neck squamous cell carcinoma (2 papers, 2021 to 2025). A squamous cell carcinoma that arises from any of the following anatomic sites: lip and oral cavity, nasal cavity, paranasal sinuses, pharynx, larynx, and salivary glands. "For example, although loss of KDM5D increased DTX resistance in our study, elevated KDM5D expression has been associated with platinum resistance in head and neck squamous cell carcinoma, where KDM5D knockdown restored platinum sensitivity." (PMID 41308413, 2025). "Nevertheless, when KDM5D abundance was alternatively split at the lowest quartile, significance was retained for both head-neck squamous cell carcinoma (HR 1.75 [95% CI 1.3, 2.5], P = 0.0011) and liver hepatocellular carcinoma (HR 1.82 [95% CI 1.1, 2.9], P = 0.0099)." (PMID 34127738, 2021).
leukemia (2 papers, 2022 to 2025). A malignant (clonal) hematologic disorder, involving hematopoietic stem cells and characterized by the presence of primitive or atypical myeloid or lymphoid cells in the bone marrow and the blood. "Kdm5d-deficient HSPCs and low-KDM5D-expressing AML patients also shared the common leukemia-promoting HALLMARK_MYC_TARGETS_V2 pathway (human: NES = 1.88, P = 0.00; mouse: NES = 2.07, P = 0.00), which was consistent with those in both mouse and human mLOY AML." (PMID 35132955, 2022). "Further efforts might be needed to explore the functional role of KDM5D in leukemia." (PMID 41431699, 2025).
metastatic disease (2 papers, 2022 to 2025). "This variability could be lost due to metastatic disease when losing portions of the Y chromosome with resultant in loss of KDM5D and fewer specimens may have KDM5D to regulate MYBL2." (PMID 36087093, 2022).
prostate adenocarcinoma (2 papers, 2022). "Using chromatin immunoprecipitation sequencing (ChIP‐seq) of the LNCaP cell line (androgen‐sensitive human prostate adenocarcinoma) with and without silenced KDM5D, MYBL2‐binding sites were analyzed." (PMID 36087093, 2022). "In contrast, the expression of KDM5D was significantly decreased in 24 kinds of tumor tissues, such as PAAD, BRCA, and prostate adenocarcinoma (PRAD)." (PMID 35493099, 2022).
adrenocortical carcinoma (1 paper, 2023). "On the other hand, transcript levels of KDM5D were significantly decreased in 14 types of cancer, including PDAC, adrenocortical carcinoma (ACC) and colonic adenocarcinoma (COAD), compared to paraneoplastic or normal tissues." (PMID 37880235, 2023).
atherosclerosis (1 paper, 2017). A disease characterized by the build-up of fatty material and calcium deposition in the arterial wall resulting in partial or complete occlusion of the arterial lumen. "Further research on lnc-KDM5D-4 should be done to study the role of this Y-linked lincRNA in steatosis-associated atherosclerosis." (PMID 29196750, 2017). "Our findings provide the first evidence for the implication of lnc-KDM5D-4 in key processes related to fatty liver and cellular inflammation associated with atherosclerosis and CAD in men." (PMID 29196750, 2017). "Following that, the Human Atherosclerosis RT2 Profiler PCR Array was used to compare cells transfected with the lnc-KDM5D-4_GapmeR_1 and cells transfected with the control GapmeR (Scramble)." (PMID 29196750, 2017).
Autoimmunity (1 paper, 2016). The occurrence of an immune reaction against the organism's own cells or tissues. "UTY demethylates the repression-associated modified histone H3K27me3, whereas KDM5D demethylates the activation-associated modified histone H3K4me3, a prominent target for anti-nuclear autoimmunity in female (NZW×B6.Lbric)F1 mice." (PMID 27483354, 2016).